ASIP (agouti signaling protein)
Description:
Signaling protein that functions as an antagonist of melanocyte-stimulating-hormone receptor MC1R, thereby playing a role in the regulation of melanogenesis. Binding to MC1R prevents alpha-MSH-induced signaling and inhibits cAMP production, resulting in down-regulation of eumelanogenesis (brown/black pigment) and increased pheomelanin (yellow/red pigment) synthesis (By similarity). In higher primates, Agouti may affect the quality of hair pigmentation rather than the pattern of pigment deposition. May also play a role in neuroendocrine aspects of melanocortin action.
Synonyms: ASP; AGTI; AGTIL; AGSW; SHEP9
Tractability: Antibody: UniProt places it where antibodies can reach, with high confidence; UniProt predicts a signal peptide or a membrane-spanning region; its Gene Ontology location is reachable by antibodies, with medium confidence.
Gene: Protein-coding gene on chromosome 20 (34,194,569 to 34,269,346, forward strand). Ensembl gene ENSG00000101440.
Subcellular location: Secreted
Subcellular location (Human Protein Atlas): Vesicles; Flagellar centriole; Mid piece; Predicted to be secreted
Gene Ontology:
Molecular function: melanocortin receptor binding; neuropeptide hormone activity; receptor antagonist activity; signaling receptor binding; type 1 melanocortin receptor binding; type 3 melanocortin receptor binding; type 4 melanocortin receptor binding
Biological process: negative regulation of melanin biosynthetic process; cell-cell signaling; generation of precursor metabolites and energy; melanin biosynthetic process; negative regulation of adenylate cyclase-activating G protein-coupled receptor signaling pathway; signal transduction; hormone-mediated signaling pathway; positive regulation of melanin biosynthetic process
Cellular component: extracellular region
Genetic constraint (gnomAD): Loss-of-function variants: 12 observed, 10.2 expected, observed/expected ratio (o/e) 1.18, 90% interval 0.75 to 1.79. The upper end of that interval is the gene's LOEUF score, 1.79, which puts it in group 6 of 6, group 1 being the genes least tolerant of losing a copy. Missense variants: 180 observed, 161.23 expected, observed/expected ratio (o/e) 1.12, 90% interval 0.99 to 1.26. Synonymous variants: 70 observed, 65.69 expected, observed/expected ratio (o/e) 1.07, 90% interval 0.88 to 1.3.
Homologues: Orthologues: chimpanzee ASIP (98% identical), macaque ASIP (93% identical), dog ASIP (81% identical), pig ASIP (81% identical), mouse a (78% identical), rabbit ASIP (78% identical), guinea pig ASIP (76% identical), rat Asip (68% identical), zebrafish asip1 (32% identical). Paralogues in human: AGRP (26% identical).
Diseases named in the same sentence as ASIP in open-access papers:
ASIP is named in the same sentence as 35 diseases in open-access papers, as found by Europe PMC text mining. Sharing a sentence is not in itself a finding about the gene and the disease. The quoted sentences say what the papers report.
melanoma (35 papers, 2011 to 2026). A malignant, usually aggressive tumor composed of atypical, neoplastic melanocytes. "Several of their findings were replicated including C4A, MICA and MICB associated with multiple cancers as well as ASIP with skin cancers (basal cell, squamous cell carcinoma and melanoma in our analysis)." (PMID 41358317, 2025). "In this study, the ASIP risk haplotype TG was found to significatively affect melanoma survival with respect to the most common GG haplotype." (PMID 40869905, 2025). "Increased expression of ASIP in the skin is associated with variants that increase the risk for melanoma in PD patients who possess the appropriate combination of these variants and can thus be genetically identified." (PMID 38263313, 2024). "ASIP regulates pigment synthesis and is strongly associated with the risk of melanoma and melanoma survival." (PMID 38263313, 2024). "Several genetic loci are associated with obesity and melanoma risk, including Agouti signaling protein, interferon regulatory factor 4, peroxisome proliferator-activated receptor-coactivator 1 and vitamin D receptor." (PMID 37777736, 2023). "In fact, the causal calls for TREM2 (LOAD), SVEP1 (T2D), and ASIP (malignant melanoma) were validated, using a two-sample MR analysis." (PMID 35079000, 2022). "For example, the E318K variant in MITF, combined with MC1R R alleles and other haplotypes in e.g., ASIP, were all at elevated frequencies in people with multiple primary melanomas compared to people with a single primary melanoma." (PMID 33681261, 2021). "Specifically, the ASIP gene has been associated with obesity in mice and somatic malignant melanoma in grey horses." (PMID 32486210, 2020). "Mutations in human ASIP are also moderate risk factors for melanoma, albeit ones with low penetrance." (PMID 27028866, 2016). "The ASIP region is one of four known melanoma-susceptibility regions and includes the four genes (RALY, EIF2S2, CHMP4B and ASIP)." (PMID 26083354, 2015). "Mutations within the ASIP gene have been implicated in altering the severity of melanoma." (PMID 41148223, 2025). "Notably, the regulatory variants associated with CHMP48 and melanoma also regulate the expression of ASIP in human skin." (PMID 38263313, 2024). "Importantly, we found that serum ASIP levels were supported as causally related to malignant melanoma (P = 1.1 × 10−17) using a two-sample MR analysis on the protein-to-outcome causal sequence of events." (PMID 35079000, 2022). "Furthermore, genome-wide association studies revealed associations of variants at the ASIP locus with skin color, melanoma risk and red hair color, pointing toward a physiological function in hair and skin pigmentation similar to other mammals." (PMID 36536132, 2022). "In addition to grey level, the Grey mutation was found to strongly influence melanoma, vitiligo and speckling grade as well as to capacitate the effects of the loss-of-function mutation at the agouti (ASIP) locus on melanoma grade." (PMID 23408897, 2013). "The ASIP gene inhibits MC1R shifting melanin color to a less protective isoform; this gene has also been associated to high-risk phenotype and melanoma susceptibility." (PMID 40869905, 2025). "By contrast, a later study found an association of OCA2 variations with BCC risk and also confirmed increased melanoma risk for variations in TYRP1, SLC45A2, and ASIP and increased SCC risk (squamous cell carcinoma) for TYR and ASIP." (PMID 39682251, 2024). "For example, microphthalmia-associated transcription factor (MITF) plays an important role in skin color and melanoma and the agouti signaling protein (ASIP) is a major regulator of mouse pigmentation." (PMID 37946423, 2024). "This article narratively reviews the role of some genetic features related to melanoma formation in horses, such as STX17 mutation, ASIP or MITF alterations, and the link between the graying process and the development of these tumors." (PMID 36670786, 2023).
melanoma (continued). "We also found that the expression of ASIP and CDK10 was associated with hair colour, melanoma and basal cell carcinoma." (PMID 33248005, 2021). "The results also included 10 SNPs previously identified for melanoma risk reported at MC1R (2 SNPs), MX2, TERT/CLPTM1L, PLA2G6, CASP8, ACTRT3, ASIP, CDC91L1, and ARNT/SETDB1/LASS2ANXA9/MCL1/CTSK." (PMID 27993549, 2017). "Inhibition of MC1R by its physiologically relevant competitive inhibitor, agouti signaling protein (ASIP), reduced melanin synthesis and morphological heterogeneity in murine B16-F10 melanoma cells." (PMID 27028866, 2016). "A role for MC1R as a growth receptor for melanoma is in agreement with transcriptome analysis of a human melanoma cell line in which MC1R was inhibited by transient transfection of an ASIP cDNA." (PMID 27028866, 2016). "Taken together these findings indicate that the in vivo doubling time for ASIP-expressing melanoma cells was approximately 2-fold longer than that of ASIP-negative tumor cells." (PMID 27028866, 2016). "Consistent with inhibition of MC1R signaling, treatment with ASIP leads to a decrease in proliferation in a mouse melanoma cell line and an increase in melanocyte migration." (PMID 27303435, 2016). "The additive component of ASIP was significantly different from zero only for melanoma grade (h2ASIP = 0.02)." (PMID 23408897, 2013). "ASIP has three genotypes, so the melanoma grade is expected to change by 0.38 units (2αASIP) when moving from an AA to an aa genotype." (PMID 23408897, 2013). "The additive component of ASIP was significantly different from zero only for melanoma (h2ASIP = 0.02)." (PMID 23408897, 2013). "Recent GWAS have unveiled association between SNPs or genetic variants in MC1R, TPCN2, ASIP, KITLG, SLC24A5, TYR, IRF4, OCA2/HERC2, SLC24A4, SLC45A2, TYRP1, and pigmentation as well as melanoma." (PMID 21559390, 2011). "Indeed, ASIP protein is the antagonist of MC1R and GWASs have highlighted an association between ASIP polymorphisms and the risk of melanoma." (PMID 40869905, 2025). "Notably, ASIP mutations have been linked with the development of facial pigmented lesions and associated with a heightened melanoma risk, as indicated by a 5-fold increase in the hazard of death from melanoma in the presence of the ASIP TG/TG diplotype." (PMID 41148223, 2025). "Genetic analyses further support shared susceptibility, as pigmentation-related variants near ASIP (encoding agouti signaling protein), TYR (encoding tyrosinase), and TYRP1 (encoding tyrosinase-related protein 1) were associated with both melanoma and BCC in European populations." (PMID 41374951, 2025). "As a potential new target for melanoma therapy, mimetic peptides derived from ASIP may be useful in biased inhibition of pro-melanoma functions of MC1R although only a few variants of ASIP have been examined." (PMID 27028866, 2016). "While ASIP stimulates opposite effects, that is, de-differentiation of melanocytes, human melanoma and murine B16-F1 melanoma cells, and increases their migration in wound healing assays, the effect of ASIP induced MC1R signaling on melanoma colonization in vivo is not known." (PMID 27028866, 2016). "Many pigmentation genes linked to melanoma in recent GWAS such as TPCN2, ASIP, KIT, NCKX5, TYR, IRF 4, OCA2 and TYRP1 have been linked to melanoma and some of them like MC1R have dual roles in pigmentation and immune responses but many other functions of these genes remain to be discovered." (PMID 23796690, 2013). "When this study was conceived, we hypothesized that while the effects of STX17 are large for all four traits and ASIP has a considerable effect of melanoma, a large part of the genetic variation remains unexplained." (PMID 23408897, 2013). "In addition, ASIP gene expression was associated with self‐reported and diagnosed malignant melanoma, and BCC in both skin tissues, and CDK10 was associated with self‐reported and diagnosed malignant melanoma, and BCC in unexposed skin." (PMID 33248005, 2021).
melanoma (continued). "Few high penetrance genes are known in Malignant Melanoma (MM), however, the involvement of low-penetrance genes such as MC1R, OCA2, ASIP, SLC45A2 and TYR has been observed." (PMID 23537197, 2013). "This study suggests that the circulating proteins ASIP, KRT5, CTSS, and TNFSF8 are causally associated with melanoma and non-melanoma skin cancer-related traits through a multicenter Mendelian randomization." (PMID 39003418, 2024). "In conclusion, while we cannot rule out PIGU as a candidate gene for malignant melanoma, these findings point to an alternate, and possibly more biologically relevant candidate, ASIP." (PMID 35079000, 2022). "An analysis of this data set for melanoma including ASIP revealed no substantial increase of heritability (h2ASIP = 0.03) while the effect of ASIP on other traits remained non-significant." (PMID 23408897, 2013). "Growth inhibition was not noted when ASIP was overexpressed in A2058 human melanoma cells in vitro." (PMID 27028866, 2016).
Obesity (10 papers, 2012 to 2025). Accumulation of substantial excess body fat. "A tandem duplication at ASIP, leading to aberrant ASIP expression pattern, was found to cause obesity associated with red hair." (PMID 39237720, 2025). "Taken together, our data indicate that ubiquitous ectopic ASIP expression is likely a monogenic cause of human obesity." (PMID 36536132, 2022). "Compared to the obesity cohort, most patients carrying the ASIP mutation have a BMI SDS and height SDS above the median." (PMID 36536132, 2022). "The current study focused on a particular adipokine the agouti signaling protein (ASIP) which has been associated with obesity and insulin resistance in studies in mice and humans." (PMID 29559925, 2018). "Mice with the ASIP mutation had a yellow coat color but also suffered from obesity, hyperglycemia, hyperinsulinemia, an increased susceptibility to hyperplasia and carcinogenesis, and ultimately lethality." (PMID 27698666, 2016). "Heterozygotes display an ectopic expression of ASIP resulting in obesity, insulin resistance, and increased tumor susceptibility, beside yellow coat color." (PMID 22530003, 2012). "Hence, the concordant phenotype associated with ectopic expression of ASIP in our participants is likely a new monogenic obesity cause in humans." (PMID 36536132, 2022). "Expression of ASIP is normally limited to the skin, where it affects pigmentation, while ubiquitous expression of ASIP causes other physiological functions, such as its expression in central nervous system resulting in obesity by inhibiting the function of MC4R." (PMID 36291616, 2022). "In summary, we report that a genomic rearrangement leads to ubiquitous expression of ASIP in patients with severe early-onset obesity and overgrowth." (PMID 36536132, 2022). "Since human ASIP is mainly expressed in adipose tissue, a role of this protein in the development of metabolic disorders like obesity and insulin resistance was assumed early." (PMID 22530003, 2012). "We screened a targeted 20 patients with a phenotype indicative of defects in the POMC pathway (extreme obesity and red hair color) for ASIP variants originally suspected but not diagnosed for POMC deficiency." (PMID 36536132, 2022). "Beside its role in melanogenesis, the agouti signaling protein (ASIP) has been related to obesity." (PMID 22530003, 2012). "This phenotype is concordant with mouse agouti obesity models ectopically expressing the homolog nonagouti/ASIP." (PMID 36536132, 2022). "The agouti locus (agouti signaling protein, ASIP) was the first obesity gene to be cloned in mice." (PMID 22530003, 2012).
skin cancer (7 papers, 2018 to 2025). "The current study gives a causal basis to substantiate previous observational studies on the association between ASIP and skin cancer risk." (PMID 39003418, 2024). "The ASIP SNPs, rs4911414 and rs1015362, are associated with increased sun sensitivity and with increased skin cancer risk." (PMID 29518100, 2018). "Similarly, an SVA in an intron of the ASIP gene that was associated with lighter skin pigmentation, an increased risk for skin cancer and changes to the splicing of the ASIP gene." (PMID 40510242, 2025). "Therefore, higher levels of ASIP expression may increase the risk of skin cancer by reducing MC1R activity and melanin production." (PMID 39003418, 2024). "ASIP was colocalized with all three types of skin cancer and STX8, KRT5, GSK3A, CTSS, and TNFSF8 with BCC." (PMID 39003418, 2024). "Proteins, ASIP, KRT5, CTSS, and TNFSF8, have the potential as diagnostic and therapeutic targets for skin cancers, and validation through future biological experiments is required." (PMID 39003418, 2024). "This multidimensional approach nominates ASIP, KRT5, CTSS, and TNFSF8 as potential diagnostic and therapeutic targets for skin cancers." (PMID 39003418, 2024). "Besides that, ASIP was strongly linked with BCC, MM, and other malignant skin neoplasms, and KRT5 with BCC and other malignant skin neoplasms." (PMID 39003418, 2024). "The correlations of ASIP and KRT5 with the three types of skin cancer remained consistent with the initial analysis results." (PMID 39003418, 2024). "Firstly, when we compared the genetic correlation, and the MTAG results before and after excluding genomic regions (HLA, ASIP, IRF4, MC1R, SLC45A2 and CDKN2A) with very large effect sizes for skin cancers and pigmentation traits, and there was a high concordance." (PMID 36496446, 2022).